SOX10 (SRY-box transcription factor 10)
Diseases named in the same sentence as SOX10 in open-access papers (continued):
Sharing a sentence is not in itself a finding about the gene and the disease.
melanoma (continued). "We performed Gene Set Enrichment Analysis (GSEA) for SOX10 and MITF ChIP-seq in 501mel melanoma line and TFAP2A in human primary melanocytes on the tiles ranked according to their activity." (PMID 34874265, 2021). "SOX10 and MITF both represent established lineage TFs in melanocytes and in melanoma, and TFAP2 has been found to co-occur with MITF in active regulatory elements in melanocytes." (PMID 34874265, 2021). "Similar to SOX10 and YY1, SALL4 is upregulated in melanoma cells and is essential for primary tumor formation and proliferation." (PMID 34417458, 2021). "Most of the MM cases (85.71%) were positive for both conventional- and conventional-adapted pan-melanoma cocktail (triple positivity for HMB-45, tyrosinase, and SOX10) with a significantly higher rate compared with naevi (p < 0.0001)." (PMID 33801642, 2021). "The Venn diagram outlined that 37.14% of the 105 MMs (n = 39) displayed positivity for all the examined markers: S100, SOX10, SOX11, MITF, and conventional pan-melanoma cocktail." (PMID 33801642, 2021). "The evaluation of SOX-10 expression by both IHC and quantitation of SOX10 RNA expression in routine veterinary diagnostics is of limited use for diagnosing melanomas, similar to the evaluation of S100 or MITF expression." (PMID 34422947, 2021). "The rate of positivity for the conventional-adapted pan-melanoma cocktail (triple positivity for HMB-45, tyrosinase, and SOX10) was 38.63% (n = 17)." (PMID 33801642, 2021). "This set of 33 fitness genes related to melanoma included melanocyte‐specific transcription factors such as MITF and SOX10, established as fitness genes for cells of the melanocytic lineage." (PMID 32767816, 2021). "One gene within the neural crest program, sox10, is a critical regulator of NCC development and is also upregulated in both zebrafish and human melanomas." (PMID 34099848, 2021). "In conclusion, our study demonstrates the essential role of SOX10 and GAPDHS in melanoma glycolysis and highlights their potential as therapeutic targets in melanoma management." (PMID 34249897, 2021). "In contrast to SOX10, RUNX2 can increase the expression of several receptor tyrosine kinases including EGFR in melanoma." (PMID 33916908, 2021). "Taken together, these findings suggest that PITX1 plays a suppressor role in the proliferative phenotype of melanoma cells as an upstream transcription factor of SOX9 and SOX10." (PMID 34526609, 2021). "As early as 48 h after changing to control medium, we detected a full recovery to the endogenous β-catenin and SOX10 protein expression levels in both TKI-sensitive and -resistant melanoma cell lines." (PMID 32238882, 2020). "In this context, PRMT5 control of SKI enhances melanoma growth by upregulating SOX10 and PAX3, which drive melanoma growth." (PMID 32743345, 2020). "However, reduced Fbxw7α might contribute to the upregulation of SOX10 in melanoma cells." (PMID 33344444, 2020). "Evidence for cobinding of SOX10, MITF, and TFAP2A was previously observed by enrichment of both MITF and TFAP2A motifs in SOX10 ChIP-seq data in melanoma cells." (PMID 32732264, 2020). "Melanoma cell properties are likely controlled by a concerted cooperation of CD271 and SOX10 as the down regulation of either CD271 or SOX10 showed comparable effects." (PMID 32878000, 2020). "In a screen for lncRNAs targeted by the melanoma transcription factors MITF and SOX10, DIRC3 was identified as a top hit and characterized as a melanoma tumor suppressor." (PMID 33329688, 2020). "The mRNA levels of many transcriptional regulators that affect the level of pigmentation, including Sox10, Ets1, and Irf4, were also reduced while the expression of Tfap2 was strongly increased in both Melb-a melanoblasts and SK-MEL-147 melanoma cells." (PMID 32151278, 2020). "SOX10 binds in the promoter region of MITF and hence is expressed in all congenital naevi and melanomas." (PMID 32899370, 2020).
melanoma (continued). "FTO knockdown increases m6A enrichment in the critical melanoma-promoting genes including PD-1 (PDCD1), CXCR4, and SOX10, and decreases their mRNA stability." (PMID 31239444, 2019). "Taken together, these data provide strong evidence that DIRC3 is transcriptionally repressed by SOX10 and MITF in melanoma." (PMID 31881017, 2019). "Remarkably, proliferative melanoma samples express high levels of MITF (melanocyte inducing transcription factor), SOX10 (SRY-box 10) and PAX3 (paired box 3) genes." (PMID 31383874, 2019). "Based on our findings together with others, we propose that SOX10 inhibits SOX9 and/or SOX9 promoter is methylated that maintain SOX9 expression at low or sub-optimal level in primary melanoma." (PMID 30642390, 2019). "In summary, we have demonstrated that FTO inhibition suppresses melanoma tumorigenicity and the expression of melanoma cell-intrinsic genes PD-1 (PDCD1), CXCR4, and SOX10, at least partially through YTHDF2-mediated mRNA decay." (PMID 31239444, 2019). "Lastly, SOX10 or high SOX9 regulates focal adhesion turnover and Rho GTPase signaling to promote mesenchymal migration of melanoma cells." (PMID 30642390, 2019). "These epidermal Mcs, not observed in control mice, also expressed the melanocyte/melanoma markers S100b, Dct, microphthalmia transcription factor (MITF) and Sox10." (PMID 31685822, 2019). "In melanoma, FTO impairs IFNγ-induced killing in melanoma cells in vitro via up-regulating PD-1, CXCR4, and SOX10 through suppressing YTHDF2-mediated-degradation and inhibits response to anti-PD-1 blockade immunotherapy." (PMID 31801551, 2019). "Immunofluorescence, TCGA database and qPCR were used to analyze the correlation between the expression patterns and levels of SOX9, SOX10 and NEDD9 in melanoma patient samples." (PMID 30642390, 2019). "We selected two melanoma cell lines with low expression of SOX9, but high expression of SOX10 (cell lines Malme-3M and UACC-62)." (PMID 30683138, 2019). "Accordingly, SOX10 was required for NEDD9 expression, which partly mediated its oncogenic functions in melanoma cells." (PMID 30642390, 2019). "Both epidermal and dermal Tomato+ cells expressed melanocyte/melanoma markers S100b, Dct, MITF and Sox10." (PMID 31685822, 2019). "Third, we used m6A- seq in combinaton with RNA-seq to identify more than 1000 potential transcriptome-wide m6A-modifiedgene targets for FTO, including the melanoma-promoting genes CXCR4 and SOX10." (PMID 31239444, 2019). "Knockdown of FTO increases m6A methylation in the critical protumorigenic melanoma cell-intrinsic genes including PD-1 (PDCD1), CXCR4, and SOX10, leading to increased RNA decay through the m6A reader YTHDF2." (PMID 31239444, 2019). "Ectopic expression of TYRO3 in the murine B16:F10 melanoma cell line was sufficient to increase MITF protein levels and resulted in increased nuclear localization of SOX10, a known regulator of MITF in melanoma." (PMID 30501104, 2018). "This SOX10-dependent induction of FOXD3 by inhibition of ERK1/2 signaling is durable for at least 120 h and is also present in melanoma cells treated with a combination of RAF and MEK inhibitors." (PMID 29295999, 2018). "Here we show that SOX10 is both necessary and sufficient for RAF inhibitor-induced expression of FOXD3 in mutant BRAF melanoma cells." (PMID 29295999, 2018). "Here, the authors show that ERK1/2 mediated phosphorylation regulates sumoylation of SOX10 which activates FOXD3, and depletion of SOX10 sensitises BRAF mutant melanoma cells to RAF inhibitors." (PMID 29295999, 2018). "In the present study we analyzed HMB45, MelanA, SOX10, CK5/6, NapsinA, p63, and TTF-1 in a large cohort of NSCLC cases and demonstrate that expression of melanoma markers is rare." (PMID 30205833, 2018). "SOX10 inactivation induces a marked upmodulation of SOX9, with consequent induction of cell cycle arrest and melanoma cell death." (PMID 29156643, 2017).
melanoma (continued). "Our data also suggest a repression of SOX10 by ID3 and a role of the ID3-SOX10 axis in melanoma drug resistance." (PMID 29299138, 2017). "In melanoma, SAMMSON is the target of the melanoblast/melanoma-specific transcription factor SOX10 and its co-factor." (PMID 28350340, 2017). "We confirmed experimentally that SOX5 and SOX10 have an effect on MITF expression levels in melanoma cell lines; SOX5 down-regulation increases MITF expression, hinting at an inhibitory effect, while vice versa, SOX10 down-regulation led to MITF up-regulation." (PMID 26927636, 2016). "TYRO3 induces MITF-M expression in a SOX10-dependent manner in melanoma cells, while other studies showed the anti-correlation between MITF and AXL in melanoma cells." (PMID 27102439, 2016). "We compared basal mRNA expression levels of SOX10, MITF, FOXD3, and ERBB3 in immortalized melanocytes, and in a panel of melanomas spanning various genetic backgrounds." (PMID 27391157, 2016). "Genes (e.g. BRN2, POU2F3, and SOX10) expressed in melanoblasts, and those (e.g. JARID1B, CD271, and ABCB5) which help to endow melanoma cells with stem-like properties and cellular plasticity, are also in this network." (PMID 27149382, 2016). "To investigate the relationship between SOX10, MITF, FOXD3, ERBB3 and NRG1 in patient samples, we utilized The Cancer Genome Atlas (TCGA, SKCM), which contains a set of 474 melanoma patient samples." (PMID 27391157, 2016). "We observed a similar effect in human melanoma cells: A double knockdown of SOX5 and SOX10 partially rescued MITF expression compared to a single knockdown of SOX10." (PMID 26927636, 2016). "As SOX10, YY1, TFAP2A, and ETS1 all have important roles in melanocytes and/or melanoma, the MAREs identified here define a combinatorial signature of TFs critical for gene regulation in this lineage." (PMID 25803486, 2015). "Indeed, while we could attribute a SOX10 high/SOX9 low signature to proliferative human melanoma cell lines and to all human and murine melanoma tissues analyzed, several human melanoma cell lines reported to display invasive features exhibited SOX10 low/SOX9 high expression." (PMID 25629959, 2015). "Particularly, by decoding the sequences of the differentially active regulatory regions, we identified SOX10 and MITF as master regulators of the melanoma-proliferative cell state." (PMID 25865119, 2015). "In striking contrast to the increase in SOX10 expression, SOX9 expression levels were low in human melanocytes and further decreased with melanoma progression." (PMID 25629959, 2015). "To investigate the mRNA expression of SOX10 and SOX9 in a large set of human melanoma samples, we used of the TCGA (The Cancer Genome Atlas) database." (PMID 25629959, 2015). "Promoter-based analyses and further validation in tissue specimens revealed the neural crest lineage master regulator SOX10 and the oncogene MYC as new upstream drivers of RAB7 transcription in melanomas." (PMID 26008978, 2015). "Indeed, in human melanoma cells, loss of SOX10 not only resulted in upregulation of SOX9 expression, but also in global transcriptional changes highly similar to the changes observed upon SOX9 overexpression, indicating that these factors appear to play opposing functions in melanoma." (PMID 25629959, 2015). "When SOX10 is inactivated, SOX9 becomes upregulated and induces cell cycle arrest and death in melanoma cells." (PMID 25629959, 2015). "Exploring the mechanism of this switch, Thomas and Erickson (2009) demonstrated that FOXD3, in mouse melanoma cells or in quail neural crest cells, repressed MITF expression even in the presence of PAX3 and SOX10." (PMID 25670789, 2015). "Our study identifies the structurally related transcription factors SOX10 and SOX9 as functionally antagonistic regulators of postnatal melanocyte and melanoma development." (PMID 25629959, 2015). "SOX10, PAX3, and MITF participate in regulation of MET (HGF receptor), which is expressed at high levels in human melanoma." (PMID 24743024, 2014).
melanoma (continued). "Here we uncover the significance of CD271 expression for melanoma cell tumorigenicity and plasticity and demonstrate a CD271-dependend regulation of the neural crest specifier SOX10 and the connection to CD133." (PMID 24799129, 2014). "ChIP experiments further formally demonstrated the in vivo binding of SOX9, SOX10 and P-CREB on meloe promoter region in melanomas." (PMID 24086527, 2013). "Although this and additional factors (like JARID1B, NES, NGFR/CD271, SOX10, TDGF1/CRIPTO) have been proposed to mark melanoma CSC (reviewed in 13), the existence of CSC in melanoma tumors remains contentious." (PMID 24098529, 2013). "We show that multiple targets of Sox10 including Mc1r, the key signaling factor in skin and hair pigmentation, are involved as effectors in B16F10 melanoma cell migration." (PMID 22363655, 2012). "Among the mouse melanoma cell lines examined, however, only B16F10 showed robust down-regulation of Sox10 and inhibition of cell migration indicating that further dissection of dosage effects and/or cell line-specific regulatory networks is necessary." (PMID 22363655, 2012). "Among 142 upregulated genes in melanoma, many are known to be expressed specifically in melanocytes, including KIT, Melan-A, TYR, TRPM1, EDNRB, DCT, SOX10 and SILV." (PMID 21294715, 2011). "Along these lines, the two melanoma lines (MeWo and 501 Mel) that exhibit positive regulation of MITF by ATF2 also exhibited positive regulation of SOX10 by ATF2." (PMID 21203491, 2010). "We next assessed the effect of ATF2 on SOX10 and MITF expression in 12 additional human melanoma cell lines." (PMID 21203491, 2010). "In contrast, 6/12 melanoma lines revealed decrease in MITF expression, of which 5 also shown decrease in SOX10 expression, pointing to positive regulation of SOX10 and MITF in these melanoma cells." (PMID 21203491, 2010). "In melanoma, ATAD2 interacts with SOX10 and c-Myc, serving as a crucial gene." (PMID 41158756, 2026). "Consistently, HK2 depletion decreased SOX10 protein levels, but not SOX10 mRNA levels, in four different BRAF-mutated (V600E) melanoma cell lines." (PMID 40956859, 2025). "In melanoma, SOX10 is phosphorylated and regulated by ERK-mediated sumoylation at Lys55, a modification crucial for its transcriptional activity and target gene selection, particularly in BRAF-mutant melanoma." (PMID 40872623, 2025). "To this end, we ectopically expressed SOX10 in melanoma cell lines through the transduction of lentivirus particles carrying the sequence of the human SOX10 open reading frame (ORF) fused to Myc-DDK tag, and lacking the 5′ and 3′UTRs." (PMID 40956859, 2025). "The negativity of CD45, S100, SOX-10, and calretinin rules out hematologic, neuroectodermal (e.g., melanomas and schwannomas), and mesothelial tumors (e.g., mesothelioma)." (PMID 40026987, 2025). "S100 and SOX10 staining demonstrated strong positivity in melanoma cells with negative reaction in adjacent epithelium." (PMID 41002705, 2025). "We did not observe any relationship between melanoma aggressiveness, as defined by histopathological features such as vascular emboli, ulceration, and junctional activity, and changes in SOX10 expression." (PMID 41012776, 2025). "Although the expression of SOX2 is quite controversial, and the role of the SOX3 protein has not yet been elucidated, the SOX10 protein, another member of this family of transcription factors, has already been widely studied in melanomas." (PMID 41012776, 2025). "Protein expression levels of known melanoma markers, such as MITF, MLANA, PMEL, TYR, and SOX10, had the lowest expression in EC-Mit samples (ANOVA, FDR < 6 × 10−4) and had a significantly lower expression in the EC-like subtypes when compared to the Mit-like subtypes." (PMID 40075679, 2025). "In this regard, conventional melanocytic markers such as HMB45, MelanA, or SOX10 are most often negative in dedifferentiated melanomas." (PMID 40506928, 2025).
melanoma (continued). "The most commonly accepted markers of LMs are as follows, although this list is not exhaustive: The following markers are commonly used in the diagnosis of LMs: CD117 (c-Kit), Melan-A, tyrosinase-related protein 1 (TRP1), human melanoma black-45 (HMB45) and SRY-box transcription factor 10 Sox10." (PMID 40304347, 2025). "Melanoma cells lacking SOX10 are tolerant to MAPK inhibition (MAPKi) due to elevated TAZ-driven TEAD signaling." (PMID 41193428, 2025). "Immunohistochemical studies showed diffusely positive SOX10, Melan-A, HMB-45, preferentially expressed antigen in melanoma (PRAME) and patchy S100 immunoreactivity and were negative for p63 and GATA3, supporting the diagnosis of melanoma." (PMID 39363663, 2025). "Histopathological analysis showed no residual neoplastic cells, confirmed by negative staining for melanoma markers (SOX10) and epithelial markers (p40, AE1/AE3)." (PMID 41229492, 2025). "Markers such as S-100, Sox-10, HMB-45, MITF, and MART-1 align with malignant melanoma." (PMID 40008002, 2025). "We report a single benign acral pigmentary lesion characterized by conspicuous keratinocyte macromelanosomes, normal basal melanocyte density and architecture (Melan-A/SOX10), Fontana-Masson positivity, Perls negativity, and no histologic features of melanoma." (PMID 41426734, 2025). "However, it has been shown that the reducing expression of SOX10 or the depletion of its target SAMMSON increases the sensitivity of BRAF-mutant melanoma to MAPK inhibitors, suggesting that upregulation of SOX10 promotes resistance to inhibitor therapy." (PMID 40872623, 2025). "Moreover, their evidence supports that positive staining of both SOX-10 and MART-1 suggests the diagnosis of melanoma." (PMID 41195191, 2025). "Immunohistochemical staining confirmed the absence of melanoma metastasis (SOX10 negative) and ruled out other carcinomatous lesions (p40 and AE1/AE3 cytokeratin pool negative)." (PMID 41229492, 2025). "Histopathologic evaluation and immunohistochemical staining (i.e., SOX-10 and MART-1) are useful diagnostic tools for invasive malignant melanoma that, albeit rare, can present without known or cutaneous primary." (PMID 41195191, 2025). "SOX10 and SOX9 are functionally antagonistic regulators of melanoma development." (PMID 40342816, 2025). "In our case, H&E revealing atypical cells in a deep dermal nodule confirmed to be melanocytes with positive staining of SOX-10 and MART-1 likely favors a diagnosis of melanoma metastasis over a primary cutaneous melanoma given the absence of positive staining in the epidermis." (PMID 41195191, 2025). "The use of key immunohistochemical markers, such as S100, SOX10, Melan-A (MART1), HMB-45, and MITF, have demonstrated varying degrees of sensitivity and specificity for the diagnosis of melanoma, assessment of prognostic factors, and guiding of therapeutic decisions." (PMID 40507250, 2025). "Metastatic melanoma is characteristically negative for cytokeratins and squamous markers but shows strong positivity for melanocytic antigens, including S100, SOX10, Melan-A, HMB-45, and MITF." (PMID 41234990, 2025). "In a mouse model, SOX10 and SOX9 act as antagonistic regulators of melanoma development." (PMID 41465475, 2025). "Additional staining was performed demonstrating positive SOX-10 and focally positive MART-1 in atypical cells in deep dermal and subcutaneous tissues, confirming the diagnosis of invasive malignant melanoma." (PMID 41195191, 2025). "Initial IHC showed these atypical cells to be melanocytic in origin (SOX10 and melanoma cocktail positive; AE1/AE3 negative)." (PMID 40984891, 2025). "In all cell lines tested, the presence of A-485 led to sharply lower SOX10 protein expression regardless of EP300/SOX10 amplification status, phenotype (MITFhigh vs. MITFlow), or melanoma subtype." (PMID 38994683, 2024).